UBAP2 (ubiquitin associated protein 2)
Description:
Recruits the ubiquitination machinery to RNA polymerase II for polyubiquitination, removal and degradation, when the transcription-coupled nucleotide excision repair (TC-NER) machinery fails to resolve DNA damage. May promote the degradation of ANXA2.
Synonyms: UBAP-2; KIAA1491; bA176F3.5; FLJ22435
Tractability: PROTAC: ubiquitination databases record sites on it; its protein half-life has been measured.
Gene: Protein-coding gene on chromosome 9 (33,921,691 to 34,049,420, reverse strand). Ensembl gene ENSG00000137073.
Subcellular location: Nucleus; Chromosome; Cytoplasm
Subcellular location (Human Protein Atlas): Cytosol
Gene Ontology:
Molecular function: cadherin binding; protein binding; RNA binding
Biological process: regulation of gene expression; hematopoietic stem cell homeostasis
Cellular component: chromosome; cytoplasm; nucleus; P-body
Genetic constraint (gnomAD): Loss-of-function variants: 64 observed, 126.12 expected, observed/expected ratio (o/e) 0.51, 90% interval 0.41 to 0.62. The upper end of that interval is the gene's LOEUF score, 0.62, which puts it in group 2 of 6, group 1 being the genes least tolerant of losing a copy. Missense variants: 1,240 observed, 1,296.7 expected, observed/expected ratio (o/e) 0.96, 90% interval 0.91 to 1. Synonymous variants: 491 observed, 505.57 expected, observed/expected ratio (o/e) 0.97, 90% interval 0.9 to 1.05.
Homologues: Orthologues: chimpanzee UBAP2 (99% identical), macaque UBAP2 (97% identical), dog UBAP2 (88% identical), rabbit UBAP2 (86% identical), pig UBAP2 (85% identical), rat Ubap2 (82% identical), mouse Ubap2 (82% identical), guinea pig UBAP2 (81% identical), tropical clawed frog ubap2 (69% identical), Drosophila melanogaster lig (25% identical), Caenorhabditis elegans pqn-59 (16% identical). Paralogues in human: UBAP2L (46% identical).
Diseases named in the same sentence as UBAP2 in open-access papers:
UBAP2 is named in the same sentence as 30 diseases in open-access papers, as found by Europe PMC text mining. Sharing a sentence is not in itself a finding about the gene and the disease. The quoted sentences say what the papers report.
osteosarcoma (10 papers, 2017 to 2025). A usually aggressive malignant bone-forming mesenchymal neoplasm, predominantly affecting adolescents and young adults. "The circRNA encoded by UBAP2 is the most prominently upregulated circRNA in osteosarcoma tissues, and patients with high circUBAP2 expression are often associated with a poor OS." (PMID 30064463, 2018). "For example, hsa_circ_0001846, generated by the circularization of exons 11 to 14 of UBAP2 pre-mRNA, has been shown to sequester miR-143, thereby up-regulating Bcl-2 and promoting osteosarcoma progression." (PMID 41194937, 2025). "The present work focused on exploring the roles of circ_UBAP2 and its molecular mechanism in osteosarcoma (OS)." (PMID 35114890, 2022). "CircRNA UBAP2 increased the expression of Sema6D in osteosarcoma cells and led to cisplatin resistance via sponging miR-506-3p." (PMID 33621206, 2021). "In osteosarcoma cells, circ-UBAP2 acts as an miR-143 sponge and suppresses apoptosis by upregulating Bcl-2." (PMID 31584877, 2019). "In vitro and in vivo experiments have shown that circ-UBAP2 promotes osteosarcoma cell growth and inhibits apoptosis." (PMID 30064463, 2018). "CircRNA UBAP2 (circUBAP2) was found to be the most markedly increased circRNA in osteosarcoma tissue as compared to that in matched adjacent control." (PMID 28977896, 2017). "Here, we found that circRNA UBAP2 (circUBAP2) expression is significantly increased in human osteosarcoma tissues as compared to those in matched controls." (PMID 28977896, 2017).
hepatocellular carcinoma (6 papers, 2016 to 2025). A malignant tumor that arises from hepatocytes. "This highlights the significant association of SFPQ, DDX39B, and UBAP2 with poor prognosis in hepatocellular carcinoma patients, underscoring their potential value as prognostic markers." (PMID 39133261, 2024). "In this study, we found that ubiquitin associated protein 2 (UBAP2) was significantly downregulated in hepatocellular carcinoma (HCC) tissues compared with adjacent normal tissues." (PMID 27121050, 2016). "This study systematically analyzed the complex relationship between paraspeckle genes, angiogenesis, and tumor immunity, determining that elevated expression of SFPQ, DDX39B, and UBAP2 is closely associated with poor prognosis in hepatocellular carcinoma (HCC) patients." (PMID 39133261, 2024). "On the other hand, UBAP2 was lowly expressed in hepatocellular carcinoma (HCC) patient samples." (PMID 30558204, 2018). "Ubap2 reportedly forms a complex with Annexin A2 (ANXA2) and promotes its degradation via ubiquitination, resulting in the inhibition of hepatocellular carcinoma progression." (PMID 37339951, 2023).
ovarian carcinoma (6 papers, 2020 to 2025). A malignant neoplasm originating from the surface ovarian epithelium. "CircRNA UBAP2 sponged miR-144, elevated the expression of CHD2, and facilitated tumor progression in ovarian cancer." (PMID 38152652, 2023).
pancreatic adenocarcinoma (4 papers, 2020 to 2025). "It was identified that the expressions of CXCR4, HIF1A, ZEB1, and SDC1 in pancreatic adenocarcinoma (PAAD) were controlled by circ-UBAP2 and miR-494." (PMID 32665846, 2020). "In pancreatic adenocarcinoma (PAAD), circ-UBAP2 promotes M2 polarization of TAMs by targeting CXCR4 and ZEB1, which enhances tumor proliferation." (PMID 40296917, 2025). "In pancreatic adenocarcinoma (PAAD), circ-UBAP2-hsa-miR-494 potentially targets CXCR4 and ZEB1 transcripts." (PMID 32943996, 2020).
prostate carcinoma (4 papers, 2018 to 2022). A carcinoma that arises from epithelial cells of the prostate gland. "Until recently, the biological function of the UBAP2 gene has been studied mainly in cancers; UBAP2 is associated with the metastasis of prostate carcinoma, while conversely, UBAP2 is related to better prognosis in hepatic cellular carcinoma." (PMID 35222790, 2022). "UBAP2 which codes for ubiquitin-associated protein 2, may be interlinked with 9p13.3 chromosomal region augmentation in prostate cancer, potentially participating in tumorigenesis." (PMID 31632503, 2019). "UBAP2 was found to be overexpressed at the gene level in samples collected from castration-resistant prostate cancer patients." (PMID 30558204, 2018). "Additionally, UBAP2 expression was significantly higher in advanced prostate cancer and was even higher in metastatic prostate cancer." (PMID 30558204, 2018). "In prostate cancer cell lines, reduction of UBAP2 copy number significantly reduced cell growth." (PMID 30558204, 2018).
glioma (3 papers, 2017 to 2022). A benign or malignant brain and spinal cord tumor that arises from glial cells (astrocytes, oligodendrocytes, ependymal cells). "Nevertheless, the mechanisms underlying the oncogenic regulation of circ‐UBAP2 in glioma are still undefined." (PMID 33543830, 2021). "As for circRNA ubiquitin‐associated protein 2 (circ‐UBAP2, hsa_circ_0008344), an overexpressed circRNA in glioma, it was identified as a strong tumor driver in glioma." (PMID 33543830, 2021). "CircRNA ubiquitin‐associated protein 2 (circ‐UBAP2, hsa_circ_0008344) has been illuminated as a tumor driver in glioma." (PMID 33543830, 2021). "Nevertheless, the mechanisms underlying the oncogenic role of circ‐UBAP2 in glioma largely remain to be elucidated." (PMID 33543830, 2021). "Consequently, we explored the mechanisms underlying the oncogenic role of circ‐UBAP2, with the hope that such work might provide new circRNA/miRNA/mRNA regulatory networks in glioma development." (PMID 33543830, 2021). "miR-1205 and miR-382 were found to be involved in the regulation of circ-UBAP2 silencing on glioma cell behavior." (PMID 35883576, 2022). "UBAP2 specifically targeted miR-1205 and miR-382, which had been identified as tumor suppressors in glioma." (PMID 35883576, 2022). "Together, these results suggested that circ‐UBAP2 silencing regulated the functional behaviors of glioma cells in vitro." (PMID 33543830, 2021). "Our current findings identified that circ‐UBAP2 silencing impeded glioma malignant progression partially by downregulating GPRC5A through targeting miR‐1205 and miR‐382." (PMID 33543830, 2021). "Considering the oncogenic regulation of circ‐UBAP2 in glioma, we here sought to identify the molecular basis governing it." (PMID 33543830, 2021). "To elucidate the mechanism of circ‐UBAP2 function on glioma progression, we undertook to search its targeted miRNAs using the prediction tool CircInteractome." (PMID 33543830, 2021). "As expected, miR‐1205 and miR‐382 levels were significantly increased by circ‐UBAP2 silencing, and they were strongly reduced by the elevated expression of circ‐UBAP2 in the two glioma cell lines." (PMID 33543830, 2021). "Here, we first demonstrated that miR‐1205 and miR‐382 were two molecular mediators of circ‐UBAP2 in modulating glioma cell progression." (PMID 33543830, 2021). "In summary, our current work demonstrated that circ‐UBAP2 silencing impeded glioma malignant progression by downregulating GPRC5A by targeting miR‐1205 and miR‐382." (PMID 33543830, 2021). "To test the functional role of circ‐UBAP2 on glioma progression, we performed “phenocopy” silencing using siRNAs targeting circ‐UBAP2 (si‐circ‐UBAP2 and si‐circ‐UBAP2#1)." (PMID 33543830, 2021). "Using CircInteractome prediction tool, we confirmed that circ‐UBAP2 directly targeted miR‐1205 and miR‐382, which had been highlighted as tumor inhibitors in glioma." (PMID 33543830, 2021). "Here, we identified two novel mechanisms, the circ‐UBAP2/miR‐1205/GPRC5A and circ‐UBAP2/miR‐382/GPRC5A axes, in the development of glioma, highlighting circ‐UBAP2 inhibitor as a potential therapeutic strategy for glioma." (PMID 33543830, 2021). "Consistent with a previous study, we demonstrated that circ‐UBAP2 silencing performed an antitumor activity in glioma in vitro and in vivo." (PMID 33543830, 2021). "Taken together, these results indicated that miR‐1205 and miR‐382 represented two importantly downstream mediators of circ‐UBAP2 function in glioma cell behaviors in vitro." (PMID 33543830, 2021). "Here, our data supported the oncogenic activity of circ‐UBAP2 in glioma in vitro and in vivo." (PMID 33543830, 2021). "To examine whether circ‐UBAP2 modulated glioma cell behaviors in vitro by the two miRNAs, we used miRNA inhibitors (anti‐miR‐1295 and anti‐miR‐382) to deplete miR‐1205 or miR‐382 in circ‐UBAP2‐silencing A172 and U251 cells." (PMID 33543830, 2021).
glioma (continued). "Moreover, the levels of miR‐1205 and miR‐382 inversely correlated with circ‐UBAP2 expression in glioma tissues." (PMID 33543830, 2021). "miR‐1205 and miR‐382 mediated the regulation of circ‐UBAP2 silencing on glioma cell behaviors." (PMID 33543830, 2021). "In this report, our data supported the significant overexpression of circ‐UBAP2 in glioma." (PMID 33543830, 2021). "Furthermore, circ‐UBAP2 mediated GPRC5A expression through miR‐1205 or miR‐382 in glioma cells." (PMID 33543830, 2021). "However, it remains unknown whether the oncogenic effect of circ‐UBAP2 on glioma is mediated by miR‐1205 or miR‐382." (PMID 33543830, 2021). "UBAP1 has also been reported fused, in-frame, with UBAP2 in one breast cancer tumor, with ADAMTSL1 in one low grade glioma." (PMID 28423358, 2017). "In contrast to the corresponding negative control, circ‐UBAP2 level was dramatically elevated in glioma tissues and cell lines." (PMID 33543830, 2021). "Our results also showed that the overexpression of circ‐UBAP2 did not affect cell colony formation, migration, invasion, and apoptosis (Figure [Link], [Link], [Link], [Link], [Link], [Link], [Link], [Link]), which was different to glioma cells." (PMID 33543830, 2021).
diabetic retinopathy (2 papers, 2021 to 2023). "Hsa_circ_0001850_circ_0001850 (circ-UBAP2) is reported to be upregulated in diabetic retinopathy (DR)." (PMID 34608841, 2021).
pancreatic cancer (2 papers, 2021 to 2024). "In pancreatic cancer, another study revealed that circ-UBAP2 and hsa-miR-494 can modulate the expression of CXCR4, HIF1A, ZEB1, and SDC1." (PMID 34496886, 2021). "CXCR4 and ZEB1 expression is positively associated with the expression of CTLA-4 and PD-1, indicating that circ-UBAP2 might repress antigen presentation and promote immune escape in pancreatic cancer." (PMID 34496886, 2021).
triple-negative breast carcinoma (2 papers, 2019 to 2020). An invasive breast carcinoma which is negative for expression of estrogen receptor (ER), progesterone receptor (PR), and human epidermal growth factor receptor 2 (HER2). "In triple-negative breast cancer (TNBC), upregulated circ-UBAP2 binds to and inhibits miR-661, which promotes high expression of the MTA1 oncogene that activates TNBC cell proliferation and migration." (PMID 31584877, 2019).
cervical cancer (1 paper, 2020). A primary or metastatic malignant neoplasm involving the cervix. "Increasing researches have reported that circular RNA UBAP2 (circUBAP2) may be a potential prognosis biomarker and participate in the development of several cancers; however, the role of circUBAP2 in cervical cancer (CC) remains largely unclear." (PMID 32760224, 2020).
diabetes (1 paper, 2020). "In Open Targets Genetics, genes near the ZBTB38, UBAP2 and ZNF236 loci show associations with various cancers, diabetes and obesity (no relevant mouse data available for these genes)." (PMID 33290408, 2020).
infertile (1 paper, 2017). "The list of genes also includes UBAP2 (ubiquitin associated protein 2), whose expression was reduced by 52-fold reduction expression in spermatozoa of oligozoospermic infertile men." (PMID 28582417, 2017).
osteoporosis (1 paper, 2023). A condition of reduced bone mass, with decreased cortical thickness and a decrease in the number and size of the trabeculae of cancellous bone (but normal chemical composition), resulting in increased fracture incidence. "The rs2781 SNP in UBAP2 gene is suggestively associated with osteoporosis and BMD with p-values of 6.1 × 10−7 (odds ratio = 1.72) and 1.1 × 10−7 in the case-control and quantitative analyzes, respectively." (PMID 37339951, 2023). "We compared the mRNA expression levels of UBAP2 and bone remodeling-related genes encoding proteins involved in osteoblast and osteoclast differentiation in the control and the osteoporosis group." (PMID 37339951, 2023). "We identify ubiquitin-associated protein 2 (UBAP2) as a novel susceptibility gene associated with osteoporosis through an exome-wide association study in women." (PMID 37339951, 2023). "The authors identify UBAP2 as a novel osteoporosis susceptibility gene by performing association studies focusing on coding regions of the genome, and report that it plays a role in bone homeostasis through the regulation of bone remodelling." (PMID 37339951, 2023). "Because UBAP2 mRNA expression was correlated with the osteoclastogenesis-related genes ACP5 and CTSK in the bone marrow samples of patients with osteoporosis, we further investigated to identify the UBAP2 associated molecule(s) involved in osteoclast differentiation." (PMID 37339951, 2023). "Human sample studies show that UBAP2 mRNA level is significantly reduced in bone marrow, but significantly increased in peripheral blood cells, of patients with osteoporosis compared to controls." (PMID 37339951, 2023). "The levels of UBAP2 and OCN were high in the osteoporosis group compared to those in the control group, with both showing similar changes (fold changes in UBAP2 levels were correlated with those in OCN levels in the blood plasma of patients with osteoporosis)." (PMID 37339951, 2023). "In fact, in the bone marrow samples of patients with osteoporosis, Cdh1 and Fosl1 were significantly upregulated while Ubap2 was significantly downregulated." (PMID 37339951, 2023). "In contrast to the results obtained from the bone marrow samples, UBAP2 mRNA expression in the blood samples of the postmenopausal women with osteoporosis was significantly higher than those in samples from the controls." (PMID 37339951, 2023). "The increased level of UBAP2 in the blood plasma of patients with osteoporosis was confirmed using another ELISA kit examination." (PMID 37339951, 2023). "Unexpectedly, in blood samples, UBAP2 expression was significantly upregulated in patients with osteoporosis." (PMID 37339951, 2023). "UBAP2 protein level is correlated with the blood plasma level of the representative osteoporosis biomarker osteocalcin." (PMID 37339951, 2023). "UBAP2 mRNA levels are significantly reduced in bone marrow, but increased in peripheral blood, from women with osteoporosis compared to controls." (PMID 37339951, 2023). "Because blood detection is a highly beneficial biomarker trait, we further tested whether UBAP2 is detectable in human blood plasma samples in patients with osteoporosis and controls." (PMID 37339951, 2023). "Next, we examined whether UBAP2 expression is different between patients with osteoporosis and control subjects." (PMID 37339951, 2023). "We also investigated whether there was an alteration in UBAP2 expression in samples from postmenopausal women with osteoporosis and controls." (PMID 37339951, 2023). "Clustered suggestive association signals in the UBAP2 region indicate UBAP2 as a potential susceptibility gene for osteoporosis and BMD, suggesting that it might play a crucial role in the pathogenesis of osteoporosis." (PMID 37339951, 2023).
osteoporosis (continued). "Collectively, although the number of tested subjects was small, the ROC curve analysis results suggest that serum UBAP2 levels may be useful for the diagnosis of osteoporosis as an additional biomarker along with serum OCN and/or other biomarkers." (PMID 37339951, 2023). "In addition, the level of UBAP2 protein is increased in blood plasma, similar to the level of osteocalcin, in patients with osteoporosis." (PMID 37339951, 2023). "The transcript levels of UBAP2 were significantly downregulated, while those of ACP5 and CTSK were upregulated in bone marrow samples from patients with osteoporosis compared with those in controls." (PMID 37339951, 2023). "ELISA-assessed protein levels in blood plasma samples revealed that both UBAP2 and OCN were significantly high in the osteoporosis group compared to the control group, and changes in the levels of UBAP2 in the two groups were closely correlated with those of OCN." (PMID 37339951, 2023). "Thus, the upregulation of UBAP2 and OCN in the blood samples from patients with osteoporosis might compensate for elevated bone resorption in postmenopausal osteoporosis." (PMID 37339951, 2023).